TLR4 (toll like receptor 4)
Diseases named in the same sentence as TLR4 in open-access papers (continued):
Sharing a sentence is not in itself a finding about the gene and the disease.
bladder cancer (40 papers, 2012 to 2025). "Most importantly, TLR4 expression is positively associated with overall survival (hazard ratio [HR] = 0.38) and cancer-specific survival (HR = 0.15) rates in bladder cancer patients." (PMID 38139364, 2023). "Activation of TLR4 signaling in bladder cancer cells induces tumor-associated PD-L1 expression via activation of Erk and c-Jun N-terminal kinase pathways and protects tumor from CTLs killing." (PMID 28484456, 2017). "Using bladder cancer cells, B7-H1 up-regulation was shown to be induced by TLR4 signaling, and in oral Langerhans cells activation of TLR4 caused induction of B7-H1 in vitro." (PMID 28056810, 2017). "Upon MANNosylation of dendritic mesoporous silica nanoparticles (DMSNs), stimulation of TLR4 can be observed in T24 bladder cancer cells." (PMID 38554019, 2024). "TLR agonists such as Bacillus Calmette-Guérin (BCG), which targets TLR2 and TLR4, were among the first approved ligands used in cancer treatment, particularly in bladder cancer." (PMID 39451226, 2024). "For example, the prevalence of TLR4 +3725GC and CC genotypes was found to be significantly increased in bladder cancer cases compared to controls." (PMID 38542078, 2024). "In this research, we have shown that the expression of TLR4 is down-regulated during the initiation and development of bladder cancer." (PMID 34141706, 2021). "The GSEA results indicate that the TGF-β pathway and apoptosis are activated in high TLR4 bladder cancer, while G2M checkpoint and E2F targets pathways are enriched in low TLR4 bladder cancer." (PMID 34141706, 2021). "The study aims to explore the expression pattern, prognostic value, and potential mechanism of TLR4 in bladder cancer." (PMID 34141706, 2021). "Tumor-infiltrated immune cell analysis and GSEA reveal the potential function of TLR4 in the initiation and development of bladder cancer." (PMID 34141706, 2021). "The aim of this study is to evaluate the expression profile of TLR genes, especially TLR4, in bladder cancer." (PMID 34141706, 2021). "Activation of TLR4 in bladder cancer cell lines also increases the expression of PD-L1 by activating the ERK and JNK signaling pathways." (PMID 33628591, 2021). "The TLR4 expression can effectively predict oncological outcomes and drug sensitivity of bladder cancer patients." (PMID 34141706, 2021). "In vivo, P-MAPA also increased the expression of TLR2 in macrophages from Leishmania chagasi-infected dogs, and of TLR2 and TLR4 in urothelial cells from female rats treated for bladder cancer." (PMID 33299378, 2020). "The activation of Toll-like receptor 4 signaling by lipopolysaccharide stimulation induced PD-L1 expression in bladder cancer cells via activation of ERK and JNK." (PMID 25889536, 2015). "After co-stimulation the T24 human bladder carcinoma cell with E. coli and lactobacilli, TLR4 were significantly increased in both mRNA and protein level, and inhibition of TLR4 blocked the lactobacilli potentiation of NF-kappaB." (PMID 22860004, 2012). "Furthermore, the prevalence of TLR4 +3725G/C has been significantly increased in bladder cancer cases." (PMID 38542078, 2024). "Previous research has reported the expression profile of TLR genes, with a focus on TLR4, within bladder cancer, with changes in promoter methylation levels of TLR4, shedding light on alterations in infiltrating immune cells and uncovering shifts in functional pathways." (PMID 37628686, 2023). "In the early stages of bladder cancer development, TLR4 is regulated by multiple methylation sites." (PMID 34141706, 2021). "Immunohistochemistry was applied to verify the expression of TLR4 in bladder cancer." (PMID 34141706, 2021). "This research discusses the abnormal expression and prognostic value of TLR4 in bladder cancer." (PMID 34141706, 2021). "A low level of TLR4 can effectively forecast poor outcomes for bladder cancer patients." (PMID 34141706, 2021). "These outcomes provide an insight into the abnormal expression of TLR4 in bladder cancer." (PMID 34141706, 2021).
bladder cancer (continued). "Moreover, in bladder cancer it has been reported that TLR4 signaling upregulates IL-6 in a dose- and time-dependent manner." (PMID 32230799, 2020). "Additionally, TLR2/TLR4 agonists are used to treat bladder cancer." (PMID 39451226, 2024). "TLR4 is decreased in tumor tissues compared with surrounding tumor tissues or normal tissue, which is also positively correlated to the overall survival rate (hazard ratio [HR] = 0.38) and cancer-specific survival rate (HR = 0.15) of patients with bladder cancer." (PMID 34141706, 2021). "Toll-like receptor 4 (TLR4) has been identified as a potential target gene for UBC and has been shown to increase B7-H1 expression in bladder cancer cells through the ERK signaling pathway, thereby promoting the metastasis of cancer cells." (PMID 40265011, 2025). "For more than thirty years, bladder cancer has been treated with Bacillus Calmette–Guérin (BCG), the TLR2/TLR4 agonist that is the most effective TLR ligand in cancer therapy." (PMID 40143078, 2025). "In this context, SMP-105 TLR2 agonist has been proposed as an agent for the treatment of bladder cancer and TAK-242 TLR4 antagonist has been shown to exhibit antitumor effect." (PMID 41295183, 2025). "Our findings align with previous research wherein, in a mouse bladder cancer model receiving radiation therapy, NETs were found to promote their formation through the protein HMGB1 via a TLR4-dependent pathway both in vitro and in vivo." (PMID 38699144, 2024). "The TLR2/TLR4 agonist (Bacillus Calmette and Guérin) is the most effective TLR ligand in cancer therapy; it has been used to treat bladder cancer for more than thirty years." (PMID 39770406, 2024). "Currently, there are three TLRs agonists, BCG (TLR2/TLR4 agonist), imiquimod (R-837) (TLR7 agonist), and monophospholipid A (MPLA) (TLR4 agonist) approved for bladder cancer, basal cell carcinoma, and vaccine adjuvant, respectively." (PMID 37296415, 2023). "As a TLR4/2 agonist, BCG mediates MyD88-dependent innate immune response in the tumor microenvironment, contributing to the therapy of bladder cancer." (PMID 36119107, 2022). "The toll-like receptor 4 (TLR4) agonist, Bacille Calmette-Guérin, has exhibited gratifying effects in treating bladder cancer." (PMID 34141706, 2021). "Some examples are the use of BCG to treat bladder carcinoma, by activating TLR2 and TLR4, or LPS, which is a natural ligand of TLR4." (PMID 32610601, 2020). "In bladder cancer, intravesical P-MAPA immunotherapy promoted a distinct activation of the TLR2- and TLR4-mediated innate immune system, resulting in increased IFN-γ signaling (TRIF-dependent pathway), which was more effective in the treatment of this tumor." (PMID 29343281, 2018). "A TLR4 activator, BCG (Bacillus Calmette, Guérin), has been used in bladder cancer treatment for its ability to trigger the production of cytokines and enhance immune responses." (PMID 26576220, 2015). "As a classical activator of TLR4, the lipopolysaccharide (LPS) can remarkably increase the level of phosphorylated STAT3 in the human bladder cancer T24 cell line, suggesting the activation of STAT3 by TLR4 signaling." (PMID 26631279, 2015). "Interestingly, the Bacillus Calmette–Guerin vaccine is approved for the treatment of bladder cancer, where stimulation of TLR2 and TLR4 are responsible for the observed anti-cancer effect." (PMID 38256021, 2024). "Previously, these BCG-derived products (BCG-CWS or BCG-derived DNA/RNA) were found to induce apoptosis in bladder cancer cells by activating TLR2, TLR4, TLR7, and TLR9 and thus inducing the myeloid differentiation primary response gene 88 (MYD88) pathway of extrinsic apoptosis." (PMID 36248858, 2022). "However, only TLR4 can effectively predict OS (HR = 0.38 [0.23–0.64], P < 0.001) and CSS (HR = 0.15 [0.06–0.39], P < 0.001) of bladder cancer patients." (PMID 34141706, 2021). "TLR4 is a favorable prognostic gene to predict OS and CSS in bladder cancer patients." (PMID 34141706, 2021).
bladder cancer (continued). "Previously, expression of both TLR4 and TLR9 has been reported in human bladder cancer cells." (PMID 30358081, 2019). "In bladder cancer, TLR2 and TLR4 would be activated by the cell wall component of M. tuberculosis, further inducing the inflammatory responses and laying the theoretical foundation for the anti-cancer effect of BCG intravesical instillation therapy in bladder cancer." (PMID 36131933, 2022). "Previous studies have found that TLR4 is less expressed in non-myo-inundated bladder cancer." (PMID 36030212, 2022). "Cytotoxicity is assessed and the expression of Toll‐like receptor 4 (TLR4) and caveolin‐1 (CAV‐1), in the presence or absence of simulated infection with bacterial lipopolysaccharide (LPS), is evaluated using the human urinary bladder cancer cell line T24." (PMID 38554019, 2024). "In our research, TLR4, rather than other TLRs, shows prognostic value to predict OS and CSS in bladder cancer patients." (PMID 34141706, 2021).
endometritis (39 papers, 2009 to 2025). An acute or chronic, usually bacterial infectious process affecting the endometrium. "In dairy cattle, pathogenic Escherichia coli is the primary causative agent of endometritis, of which the LPS component activates the TLR4/NF-κB signaling pathway, triggering endometrial inflammation." (PMID 41463904, 2025). "Conclusively, our findings strongly suggested that ICA protects endometritis caused by LPS by suppressing TLR4-associated NF-κB and Nrf2 pathways." (PMID 36142129, 2022). "The results demonstrated the therapeutic efficacy of GnRb1 in the mouse model of LPS-triggered endometritis via the inhibition of the TLR4-associated NF-κB pathway." (PMID 34885671, 2021). "Similarly to the outcomes observed in cellular experiments, the mouse model of endometritis showed that the expression levels of NF-κB pathway-associated proteins, including TLR4, MYD88, and P-NF-κB-p65, were significantly reduced in the treatment group compared to the bacterial challenge group." (PMID 40713896, 2025). "The test showed that berberine and carvacrol downregulated the mRNA expression of TLR2 and TLR4 in the uterine tissues of endometritis mice." (PMID 40431224, 2025). "In the same vein, mentioned that gene expression levels were considerably higher in endometritis-affected cows than in resistant ones for the TLR4 gene." (PMID 40872670, 2025). "For example, miR-223 alleviates inflammation by targeting NLRP3, and miR-148a negatively regulates endometritis via TLR4 signaling." (PMID 40298790, 2025). "The buffaloes with endometritis had considerably higher expression levels of TLR4, IL-8, IL-17, NFKB, SLCA11A1, NCF4, Keap1, HMOX1, OXSR1, ST1P1, and SERP1." (PMID 39195794, 2024). "Compared to resistant cows, endometritis-affected cows produced considerably more of the genes TLR4, LITAF, TNF-α, TKT, RPIA, TLR7, TNF-α, TKT, and AMPD1." (PMID 39195794, 2024). "Intraperitoneal injection of RGZ before LPS perfusion significantly relieved endometritis, along with decreased inflammatory cell infiltration and decreased TLR4 expression." (PMID 38547218, 2024). "To further explore the protective effect of RGZ on LPS-induced endometritis, we determined the expression of TLR4 in uterine tissue in different test groups." (PMID 38547218, 2024). "Our findings showed that the buffaloes with endometritis had significantly higher TLR4, IL-8, IL-17, NFKB, SLCA11A1, NCF4, Keap1, HMOX1, OXSR1, ST1P1, and SERP1 expression levels." (PMID 39195794, 2024). "On the other hand, it was reported that the peroxisome proliferator-activated receptor γ (PPARγ) inhibits pro-inflammatory cytokines (TNFα, IL-1β, and IL-6), TLR4, and NF-κB, relieving LPS-induced endometritis in pig endometrial epithelial cells (EECs)." (PMID 39408650, 2024). "For the buffaloes with endometritis, TLR4 had the highest possible quantity of mRNA (2.62 ± 0.16) while CAT had the lowest amount (0.52 ± 0.13 mRNA) for each gene." (PMID 39195794, 2024). "Staphylococcus aureus (S. aureus)-induced endometritis mouse model was established, followed by treatment with C.t, and inflammatory response, epithelial barrier, and TLR4/NF-κB pathway were evaluated." (PMID 38816643, 2024). "For each gene examined in the endometritis-affected cows, TLR4 had the highest potential mRNA level (2.51 ± 0.11); IL10 had the lowest potential level (0.31 ± 0.06)." (PMID 37368756, 2023). "Gene expression levels were considerably higher in endometritis-affected cows than in resistant ones for the genes TLR4, TLR7, TNF-α, NCF4, LITAF, OXSR1, TKT, RPIA, and AMPD1." (PMID 37368756, 2023). "When compared to resistant cows, endometritis-affected cows had considerably higher levels of the genes TLR4, TLR7, TNF, NCF4, and LITAF expression." (PMID 37756095, 2023). "Our results suggest that C. butyricum ameliorates E. coli-induced endometritis by inhibiting the TLR4/NF-κB signaling pathway and the HDAC level." (PMID 36321897, 2022).
endometritis (continued). "Innate immunity is closely associated with the mechanisms of recovery after delivery in ruminants, and the TLR4/NF-κB signaling pathway is known to activate in E. coli-induced endometritis." (PMID 34573559, 2021). "LPS mediated its penetrating destruction of the endometrial cell walls through the pathogens recognizing receptors (PRR), and the most studied PRR in the molecular and cellular pathogenesis cascade of endometritis is the Toll-like receptor 4 (TLR4)." (PMID 34943807, 2021). "Inhibition of TLR4/NF-κB signaling to reduce LPS-induced endometritis has recently been explored in the study of disease pathogenesis and the development of therapeutic drugs." (PMID 34573559, 2021). "The compilation of the research results has demonstrated the potential of Bta-miR-24-3p in regulating the LPS-induced bovine endometritis through attenuation of TLR4/NF-ĸB cellular signaling pathway by targeting LGALS9." (PMID 34943807, 2021). "It recognized that Bta-miR-24-3p regulates LPS-triggered endometritis by suppressing the TLR4/NF-ĸB signaling pathway by targeting the LGALS9 gene." (PMID 34943807, 2021). "We then silenced and overexpressed ISG15 in the cells to explore the role of the ISGylation modification system in LPS-induced endometritis by regulation of the TLR4/NF-κB signaling pathway." (PMID 34573559, 2021). "In conclusion, our present study identifies for the first time that miR‐148a functions as a negative regulator of the inflammatory response in LPS‐induced endometritis by targeting TLR4 and its downstream pathway." (PMID 31756048, 2020). "Western blot results indicated that DI exerted its protective effects on LPS-stimulated endometritis by suppressing TLR4/NF-κB signaling pathway." (PMID 32963747, 2020). "The unique presence of TLR4 in exosomes derived from transition cows at low-risk for diseases might indicate that the targeted cells will receive additional immunity compared with cows designated as high-risk of disease and, as such, be able to better defend themselves against uterine infection." (PMID 31554846, 2019). "Molecular mechanism investigations of C.t action in endometritis revealed that the TLR4/NF-κB pathway plays a pivotal role in endometritis, e.g., catalpol has been found to inhibit inflammatory injury to the mouse uterus by suppressing the TLR4/NF-κB pathway activation." (PMID 38816643, 2024). "It has been reported that C. butyricum can improve endometritis by inhibiting the signal pathway mediated by toll-like receptor 4 (TLR4) and increasing the expression of tight junction proteins occludin and Zona occludens protein 1 (ZO-1) in the uterine tissue." (PMID 39472001, 2024). "However, the knockdown of TLR2/TLR4 significantly reduced inflammatory responses, downregulated NF-κB/p65, and elevated Nrf2 levels, thereby ameliorating endometritis." (PMID 39408650, 2024). "Moreover, C.t alleviates S. aureus-induced endometritis in mice by inactivating the TLR4/NF-κB pathway." (PMID 38816643, 2024). "Nucleotide sequence variations between healthy and endometritis-affected cows were revealed using PCR-DNA sequencing for immune (TLR4, TLR7, TNF-α, IL10, NCF4, and LITAF), antioxidant (ATOX1, GST, and OXSR1), and erythritol-related (TKT, RPIA, and AMPD1) genes were reported by44." (PMID 38459095, 2024). "In summary, C.t alleviates S. aureus-induced endometritis by inactivating the TLR4/NF-κB pathway." (PMID 38816643, 2024). "The following genes were assessed for their expression levels using real-time PCR in both the normal and endometritis-affected buffaloes: immune (TLR4, IL-8, IL-17, NFKB, SLCA11A1, and NCF4) and antioxidant (SOD, CAT, NDUFS6, Nrf2, Keap1, PRDX2, HMOX1, OXSR1, ST1P1, and SERP1)." (PMID 39195794, 2024).